SIRT1 (sirtuin 1)
Diseases named in the same sentence as SIRT1 in open-access papers (continued):
Sharing a sentence is not in itself a finding about the gene and the disease.
emphysema (30 papers, 2010 to 2025). "In the lungs of mice exposed to cigarette smoke, altered rhythms of SIRT-1 protein and core clock genes including Bmal1, Clock, Per1, Per2, Cry1, Cry2, Nr1d1, Nr1d2, and Rora were observed in a circadian manner, increasing the susceptibility to inflammation and emphysema development." (PMID 35047522, 2021). "Research indicates that AXT can alleviate cigarette-induced emphysema through a SIRT1-dependent mechanism." (PMID 40190581, 2025). "A recent study has shown that SIRT1 deficiency increases FOXO3 acetylation and exacerbates emphysema in CSE-induced mouse models, while activation of SIRT1 reduces FOXO3 acetylation and improves lung functions." (PMID 35313881, 2022). "Levels of histone deacetylase 1 (HDAC1) and sirtuin 1 (SIRT1), which are reported to participate in the mechanisms for experimental pulmonary emphysema, were significantly diminished in the lungs of the triple n/i/eNOSs−/− mice." (PMID 34764368, 2021). "Further molecular evidence also implicates the role of SIRT1 in protein/histone deacetylase and as a protective factor of the development of pulmonary emphysema." (PMID 33715628, 2021). "Reduced anti-aging protein SIRT-1 levels were found in the lungs of smokers and patients with emphysema, including AM, airway, and alveolar epithelium." (PMID 35047522, 2021). "SIRT-1 activation also protects against pulmonary emphysema via deacetylation of FOXO-3a and reduction of premature senescence in mice." (PMID 31028246, 2019). "SIRT1 protected against emphysema via FOXO3-mediated reduction of premature senescence and apoptosis in mice." (PMID 31881011, 2019). "SIRT1720, a specific activator of SIRT1, rescues CS-induced emphysema in mice via upregulation of Foxo3a, a well-known SIRT1 target." (PMID 29572511, 2018). "SIRT1 activation by genetic overexpression and a pharmacological SIRT1 activator mitigated cigarette smoking-induced and elastase-induced emphysema with the reduction in number of SAβGAL-positive epithelial cells in mice." (PMID 28245616, 2017). "GOLD stage is defined by lung function (mainly by FEV1 % predicted), but there was good correlation between SIRT1 and certain disease characteristics such as emphysema, MRC dyspnea score, 6MWD, and BODE score." (PMID 28506610, 2017). "A previous screening for host genes differentially expressed upon NTHi infection identified sirtuin-1, which encodes a NAD-dependent deacetylase protective against emphysema and is activated by resveratrol." (PMID 29038519, 2017). "Because SIRT1 is an anti-senescence gene that protects against elastase-induced emphysema via reduction of premature cellular senescence in mice, we performed immunohistochemistry for SIRT1 and senescence marker p16 in lung tissue of CS-exposed mice." (PMID 26284585, 2016). "This SIRT1-mediated protection against emphysema is reported to be catalyzed by FOXO3 transcription factor." (PMID 25907989, 2015). "Thus, it is likely that decreased HDAC1 and SIRT1 levels were also involved in the development of spontaneous pulmonary emphysema in the triple n/i/eNOSs−/− mice." (PMID 34764368, 2021). "SIRT1 protects against emphysema through FOXO3-mediated reduction of cellular senescence." (PMID 32051395, 2020). "Accordingly, SIRT1 levels may be an important factor in the estimation of some disease characteristic in patients with COPD such as emphysema." (PMID 32523885, 2020).
emphysema (continued). "In addition, enhancement of SIRT1 expression or activity inhibits stress-induced premature cellular senescence and also provides protection against cigarette smoke-induced emphysema." (PMID 25907989, 2015). "Interestingly, our preliminary data showed that overexpression of SIRT1 in ApoE-/- mice in double transgenic mice protected, whereas knockdown of SIRT1 in ApoE-/- mice aggravated the lung phenotype (inflammation and emphysema)." (PMID 20663150, 2010). "There are many other mechanisms associated with PM-induced lung damage, further studies were needed to investigate whether H2S affect these pathways in PM-induced emphysema and airway inflammation, like Sirt1, autophagy, ageing, which had interaction both with H2S and Nrf2." (PMID 32116706, 2020). "Yao and colleagues have shown that SIRT1 is reduced in the lungs of patients with COPD and activation of SIRT1 by a selective pharmacological activator, SRT1720, protects against pulmonary emphysema in mice." (PMID 31881011, 2019). "Increasing evidence indicates SIRT1 as a connecting link among oxidative stress, inflammation, and aging/senescence, all processes characterizing COPD phenotypes, especially COPD/emphysema." (PMID 26236580, 2015). "In a first study, the protein level of SIRT1 was decreased in the lung of heterozygous knockout (Sirt1+/−) mice exposed to CS and elastase and in the lung of patients with COPD/emphysema." (PMID 26236580, 2015). "Moreover, SIRT1 overexpression, by downregulation of MMP-1 and MMP-3, has beneficial effect on mice emphysema and human COPD." (PMID 33917352, 2021). "This protective role of SIRT1 in emphysema is not attributed to its effect on NF-κB-mediated inflammation." (PMID 32308644, 2020). "Furthermore, SIRT1 activation by both overexpression and pharmacological activator SRT1720 can reduce cellular senescence via the SIRT1-FOXO3 axis and then attenuate emphysema." (PMID 32308644, 2020).
hyperlipidemia (29 papers, 2013 to 2025). "In conclusion these results suggest that Nrf2, NF-κB and SIRT1 may be important targets for the treatment of myocardial injury and related diseases caused by hyperlipidemia." (PMID 34712707, 2021). "SIRT1, as a dependent acylase, is involved in lipid metabolism disorders such as hyperlipidemia, which reduces the protein expression level of SITR1." (PMID 39272560, 2024). "The role of SIRT1 regarding the relationship between hyperlipidemia and endothelial activation was also investigated." (PMID 38304233, 2023). "SIRT1 is involved in the caspase-1 pathway in early hyperlipidemia and promotes ECs activation prior to monocyte recruitment." (PMID 36632457, 2023). "Taken together, these results demonstrate that exercise can reduce hyperlipidemia-induced cardiac damage by increasing the expression of SIRT1." (PMID 37277452, 2023). "There was a significant reduction in cellular beta-oxidation capacity and concomitant hyperlipidemia after specific deletion of Sirt1 in mouse (Mus musculus)." (PMID 35903360, 2022). "On the other hand, in a mouse model of induced hyperlipidemia, the activation of caspase-1 was inhibited during early atherogenesis, facilitating the accumulation of sirtuin-1 in endothelial cells with consequent anti-inflammatory effects." (PMID 36359402, 2022). "Studies showed that Sirt1 is critical for liver function and is pivotal to improve hyperlipidemia and hepatic lipid metabolism." (PMID 34899293, 2021). "The downregulation of key HDL proteins in the small intestine in hyperlipidemia is due to decreased levels of their transcriptional activators PPARγ, LXRs, and SIRT1." (PMID 34944413, 2021). "Both maternal and paternal SIRT1 overexpression substantially reduced adiposity and hyperlipidaemia, but only the former improved glucose tolerance and adipocyte morphology in MHF offspring." (PMID 33027895, 2020). "These evidences confirm the positive effect of SIRT1 activation on hyperlipidemia." (PMID 36632457, 2023). "Notably, there are several compounds which alleviates lipid metabolism diseases such as hyperlipidemia by activating SIRT1." (PMID 36632457, 2023). "In addition, exercise increased the level of SIRT1, and then the up-regulation of SIRT1 reduced hyperlipidemia-induced cardiac oxidative stress, fibrosis, inflammation and apoptosis." (PMID 37277452, 2023). "Hence, exercise increases the level of SIRT1, and the upregulation of SIRT1 reduces hyperlipidemia-induced cardiac fibrosis and collagen accumulation." (PMID 37277452, 2023). "Hyperlipidemia decreases SIRT1 expression, resulting in opposite effects." (PMID 33806509, 2021). "This study provides the evidence that exercise could attenuate hyperlipidemia-induced leukocyte infiltration, collagen accumulation, lipid deposition, oxidative stress, fibrosis, and apoptosis, as well as reduce the downregulation of SIRT1, SOD, and GSH-Px." (PMID 37277452, 2023). "Therefore, to investigate whether the activation of SIRT1 could attenuate hyperlipidemia-induced cardiac fibrosis in vivo and whether the TGF-β/Smad pathway is involved in this process, Masson’s trichrome staining and collagen III, TGF-β, and Smad3 expression were assessed." (PMID 37277452, 2023). "Further studies are needed to explore the effects of AEE on Sirt1, which is important to understand the action mechanism of AEE on hyperlipidemia." (PMID 34899293, 2021). "A recent study has shown that pterostilbene protects against lipid accumulation by modulating the miR-34a/Sirt1/SREBP1 pathway, which corroborates the importance of miRNAs in modulating hyperlipidemia." (PMID 34439528, 2021). "In conclusion, our investigation showed that octacosanol could ameliorate hyperlipidemia in the HFD-induced mouse model, and the lipid-lowering function was mediated by multiple pathways, including AMPK/SREBP-1c/ACC, AMPK/SIRT1, PPARs, and LXR pathways." (PMID 35681357, 2022).
hyperlipidemia (continued). "Hyperlipidemia (i.e., a condition where too many lipids or fats, such as cholesterol and triglycerides, accumulate in the blood) has a negative effect on SIRT1 expression, increases localization of FOXO1 to the nucleus, and reduces insulin secretion." (PMID 33806509, 2021). "Furthermore, the mRNA expression of SIRT1 and FOXO1 slightly increased, while FAS was subsequently decreased in the perirenal adipose tissue, which demonstrated a reduction in fatty acid synthesis and therefore reduced the development of hyperlipidemia." (PMID 37835191, 2023).
lipid metabolism disorders (29 papers, 2014 to 2026). "In conclusion, our results suggest that high Sirt1 expression is associated with lipid metabolism disorder and immune infiltration, ultimately contributing to a dismal prognosis in ccRCC." (PMID 38427808, 2024). "This study aims to explore the underlying mechanism of SNN for regulating the lipid metabolism disorder in NAFLD based on the SIRT1/AMPK signaling pathway." (PMID 35945571, 2022). "These compounds reverse hepatic lipid metabolism disorders by activating the AMPK/SIRT1 and PPARα signaling pathways, inhibit lipogenesis by suppressing the key lipogenic factor SREBP-1c, and accelerate lipid catabolism by promoting fatty acid β-oxidation." (PMID 42283012, 2026). "BBM mitigates liver lipid metabolism disorders by modulating the SIRT1/LKB1/AMPK pathway, regulating the expression of autophagy markers LC3a/b, Beclin 1, and p62, and inducing autophagy to decelerate the progression of NAFLD." (PMID 39175576, 2024). "Our previous study found that MGF prevented hepatic lipid metabolic disorders via SIRT-1/AMPK pathway." (PMID 38183139, 2024). "Limited studies exist regarding the role of SIRT1 in lipid metabolism disorder in periparturient dairy cows." (PMID 32230804, 2020). "After revealing the association between miR-122 and Sirt1, we next investigated the influence of this interaction on lipid metabolic disorder in hepatocytes by knocking down miR-122 or Sirt1." (PMID 31195981, 2019). "Because SIRT1 inactivation induces lipid metabolism disorders and inflammation, there was a significant increase in the lipid deposition and MCP-1 expression in THP-1-derived macrophages." (PMID 28881659, 2017). "The latest research has disclosed that nicotinamide riboside ameliorate high-fructose-induced lipid metabolism disorder may be related to the regulation of inflammation mediated by the SIRT1/NF-κB signaling pathway." (PMID 36767748, 2023). "SNN administration could improve the lipid metabolism disorder and liver damage of NAFLD, and the regulation of the SIRT1/AMPK signaling pathway may contribute to the underlying mechanism." (PMID 35945571, 2022). "Elevating Sirt1 levels and activating the AMPK pathway protect hepatocytes from lipid metabolic disorders such as NAFLD and suppress lipogenesis." (PMID 38136219, 2023). "Another study established that inhibiting miR-122 safeguards hepatocytes from lipid metabolic disorders such as NAFLD and curbs lipogenesis by elevating Sirt1 and activating the AMPK pathway." (PMID 37915947, 2023). "AAP up-regulated Pgc1α and Sirt1 expressions, and its intervention on HFFD-induced liver lipid metabolism disorder was closely related to the regulatory effects on mitochondrial function." (PMID 35407029, 2022). "The inhibition of miR-122 protects hepatocytes from lipid metabolic disorders such as NAFLD and suppresses lipogenesis via elevating Sirt1 and activating the AMPK pathway." (PMID 31195981, 2019). "Taken together, these data suggest that SIRT1 overexpression improves NEFA-induced glucose and lipid metabolic disorders in hepatocytes." (PMID 29207650, 2017). "In summary, this study reveals that long-term moderate caloric restriction (30%) intervention and resveratrol (200 mg/kg/day) supplementation improved lipid metabolism disorder and attenuated fat accumulation in the liver tissues of HFD-fed rats by up-regulating the SIRT1-autophagy signaling axis." (PMID 28817690, 2017). "By stimulating the sirtuin 1 (SIRT1)/peroxisome proliferator-activated receptor alpha (PPARα)/Fibroblast growth factor 21 (FGF21) pathway, APS could alleviate lipid metabolism disorder, notably, by increasing hepatic glycolipid metabolism, reducing inflammation, and lipid droplet deposition." (PMID 35308224, 2022).
acute myeloid leukemia (28 papers, 2014 to 2025). Acute myeloid leukemia (AML) is a group of neoplasms arising from precursor cells committed to the myeloid cell-line differentiation. "SIRT1 is overexpressed in acute myeloid leukemia (AML), chronic myeloid leukemia (CML), diffuse large B‐cell lymphoma (DLBCL), melanoma, lung, and gastric cancer." (PMID 39215785, 2025). "Inversely, Li and coworkers reported a positive regulation of SIRT1 by the c-MYC pathway in acute myeloid leukemia." (PMID 29383100, 2017). "However, our findings are consistent with recent reports documenting the role of IRF9 in the negative regulation of the TRIF/NF-κB transcriptional response or the expression of SIRT1 in acute myeloid leukemia cells." (PMID 31426476, 2019). "SIRT1 upregulation is associated in acute myeloid leukemia (AML), and primary, prostate, colon, melanoma and non-melanoma skin cancers." (PMID 38784035, 2024). "Through SIRT1 inhibition, Salermide induced apoptosis in MOL4 acute lymphoblastic leukemia, SW480 colorectal, KG-1a acute myelogenous leukemia, and Raji Burkitt’s lymphoma cells." (PMID 34650436, 2021). "USP22 can deubiquitinate Sirt1 and enhance its stability through c-MYC-related network, leading to FLT3 tyrosine kinase inhibitors (TKIs) resistance in acute myeloid leukemia (AML)." (PMID 28567015, 2017). "Here we investigated the higher expression of SIRT1 not only in CML but also acute myeloid leukemia (AML) cells and assessed the activity of NHEJ repair by downregulating SIRT1 in these myeloid leukemia cells." (PMID 26646449, 2016). "In acute myeloid leukemia (AML), ANRIL is up-regulated in patients at diagnosis and down-regulated in patients with complete remission; it is proved to modulate the glucose metabolism related pathway of AdipoR1/AMPK/SIRT1 to promote AML cell survival." (PMID 32714094, 2020). "Additionally, silencing of SIRT1 also impaired the DNA damage repair ability with reduced NHEJ activity, leading to upregulation of cell apoptosis in THP-1 and U937, which are acute myeloid leukemia cell lines." (PMID 26646449, 2016). "For instance, in acute myeloid leukemia (AML), XBP1s was shown to transcriptionally upregulate miR-22-3p by directly targeting its host gene, MIR22HG, leading to downregulation of SIRT1 and increased chemosensitivity." (PMID 41372991, 2025). "Indeed, SIRT1 was shown to promote leukemogenesis in CML and FLT3-ITD acute myeloid leukemia (AML)." (PMID 39479446, 2024).